LINC00592 (long independently transcribed non-coding RNA 592)
Gene: Long non-coding RNA gene on chromosome 12 (52,164,115 to 52,223,880, forward strand). Ensembl gene ENSG00000258279.
Diseases named in the same sentence as LINC00592 in open-access papers:
LINC00592 is named in the same sentence as 4 diseases in open-access papers, as found by Europe PMC text mining. Sharing a sentence is not in itself a finding about the gene and the disease. The quoted sentences say what the papers report.
tumor (1 paper, 2022). "According to our study, LINC00592 is highly expressed in tumor cells and has the largest HR value." (PMID 36733364, 2022).
LINC00592 also shares sentences with these, for which no sentence is quoted: cervical cancer (2 papers); cancer (1); gastric cancer (1).